AFP (alpha fetoprotein)
Diseases named in the same sentence as AFP in open-access papers (continued):
Sharing a sentence is not in itself a finding about the gene and the disease.
lung carcinoma (continued). "In this cohort, mild elevation of AFP, ≥1.8 ng/ml, was associated with 37% increase in lung cancer among never smokers." (PMID 27805040, 2016). "Some cases of AFP-producing lung carcinoma were reported in the 1980s." (PMID 26943677, 2016). "This type of lung cancer with elevated serum AFP levels is a special variety." (PMID 24959228, 2014). "Transbronchial lung biopsy led to the diagnosis of AFP-producing lung carcinoma." (PMID 21554678, 2011). "Thus, adenocarcinoma and large-cell carcinoma account for nearly all cases of AFP-producing lung cancer, although rare cases of AFP-producing squamous cell carcinoma and AFP-producing carcinoid have also been reported." (PMID 21554678, 2011). "In conclusion, although AFP is not commonly used as a biomarker in routine lung cancer diagnosis, it may act as a key diagnostic indicator in certain subtypes and play a supportive role in predicting metastasis and assessing tumor progression." (PMID 40430002, 2025). "CEA and AFP were the targeted lung cancer biomarkers in another report in which their simultaneous determination was accomplished by modifying hollow Au nanospheres with antibodies against CEA or AFP and malachite green isothiocyanate and X-rhodamine-5-(and-6)-isothiocyanate, respectively." (PMID 37241360, 2023). "In addition, AFP is increased in patients with liver and brain metastasis of lung cancer." (PMID 34595214, 2021). "By integrating risk factors such as family history of lung cancer, CEA and AFP for light smokers, and lung function test (Maximum Mid-Expiratory Flow, MMEF25–75%), AFP and CEA for never smokers, light and never smokers with cancer risks as high as those within heavy smokers could be identified." (PMID 27805040, 2016). "However, AFP-producing lung cancer is rarely reported, and its pathological cell features and clinical symptoms remain unclear." (PMID 24959228, 2014). "Such a specificity and sensitivity is a comparable diagnostic accuracy to that reported as being of clinical utility in lung cancer and with further optimisation, has the potential to improve on the diagnostic accuracy for early stage disease, offered by gold standards in HCC (AFP/US imaging)." (PMID 25093332, 2014). "Furthermore, large-cell carcinoma accounts for 25% of all AFP-producing lung cancers." (PMID 21554678, 2011). "Nanocomposite-based electrochemical biosensors are revolutionizing lung cancer diagnosis by enabling non-invasive, rapid, and ultrasensitive quantification of protein and genetic biomarkers like CEA, NSE, and AFP from liquid biopsies." (PMID 38999110, 2024). "Several studies have demonstrated the use of DPV and SWV for the ultrasensitive quantification of lung cancer biomarkers like CEA, NSE, and AFP." (PMID 38999110, 2024). "Electrochemical biosensors have emerged as powerful tools for the ultrasensitive detection of lung cancer biomarkers like carcinoembryonic antigen (CEA), neuron-specific enolase (NSE), and alpha fetoprotein (AFP)." (PMID 38999110, 2024). "Using common protein carcinoembryonic antigen (CEA) and a-fetoprotein (AFP) as biomarkers, SERS-based detection was performed for the diagnosis of lung cancer." (PMID 36979540, 2023). "Our results also identified AFP, CEA, CA-125, CA-153, CYFRA21-1, and TPSA as six clinically available biomarkers for OM in male lung cancer patients." (PMID 32226491, 2020). "For several years, tumor protein biomarkers such as CEA, alpha-fetoprotein (AFP), and carbohydrate antigen 19–9 (CA19-9) have been extensively utilized in the screening and diagnosis of lung cancer, evaluation of treatment efficacy, postoperative monitoring, and prognostic assessment." (PMID 41573685, 2025). "Alpha-fetoprotein (AFP)-producing hepatoid adenocarcinoma of lung (HAL) is a rare type of lung cancer, with its characteristics being not yet fully clarified." (PMID 39968074, 2025).
lung carcinoma (continued). "Interestingly, we encountered a case of AFP-producing HAL in a patient with IPF, which benefit from the systematic treatment and achieved a long-term survival for this rare type of lung cancer." (PMID 39968074, 2025). "Additionally, a high-performance sensor based on a double-template molecularly imprinted polymer has been successfully utilized for the specific detection of lung cancer biomarkers carcinoembryonic antigen (CEA) and alpha-fetoprotein (AFP)." (PMID 38891543, 2024). "The clinical value of carcinoembryonic antigen (CEA), carbohydrate antigen 125 (CA-125), carbohydrate antigen 199 (CA-199), alpha-fetoprotein (AFP), neuron-specific enolase (NSE), cytokeratin 19 fragment (CYFRA21-1), and carbohydrate antigen 15 − 3 (CA15-3) in lung cancer has been widely concerned." (PMID 37773123, 2023). "Also, different biomarkers like AFP, CA125, CEA and CA15-3 represent particular characteristics of four different lung cancer." (PMID 36560548, 2022). "Relative to lung cancer patients without mediastinal lymph node metastasis, the concentrations of AFP, CEA, and CYFRA 21-1 in lung cancer patients with mediastinal lymph node metastasis were found to be extremely high, while HB was found to be lower (p < 0.05)." (PMID 36176291, 2022). "Alpha-fetoprotein (AFP)-producing lung adenocarcinoma is a rare type of lung cancer, with its characteristics not yet fully clarified." (PMID 21554678, 2011). "Only a small number of reports have been published of cases with AFP-producing lung cancer; therefore, the pathophysiology and clinical characteristics of AFP-producing lung cancer have not yet been adequately clarified." (PMID 21554678, 2011). "In addition to AFP and CEA, CSC-derived tumors contained increased levels of CA 125 and CA 72-4, which are considered biomarkers of lung cancer and provide additional target for immunotherapy." (PMID 18728788, 2008). "Since AFP-producing HAL has scarcely been reported, the clinical features and molecular mechanism of this type of lung cancer are still unclear, with no standard treatment regime being recommended." (PMID 39968074, 2025).
Hypertension (57 papers, 2014 to 2026). The presence of chronic increased pressure in the systemic arterial system. "Age, abnormal BMI, hypertension, and abnormal AFP were linked specifically to total T cell abnormalities." (PMID 39439786, 2024). "Baseline associations were age and alpha-fetoprotein levels with extrahepatic mortality, 80% due to sepsis; age with extrahepatic malignancies and hypertension; gender and hyperuricemia with CVA; and UDCA response with autoimmune disease." (PMID 31110209, 2019). "Additionally, age, abnormal BMI, hypertension, and abnormal AFP levels were linked to total T cell abnormalities, emphasizing the importance of understanding patient-specific factors in treatment outcomes." (PMID 39439786, 2024). "Age, abnormal BMI, hypertension, and abnormal AFP were linked to total T cell abnormalities." (PMID 39439786, 2024). "A 65-year-old male patient with a history of hypertension was admitted to the hospital due to a one-week increase in serum AFP levels." (PMID 39931054, 2025). "Ten parameters were obtained after further screening, including AFP, bile duct dilatation, gender, degree of differentiation, hypertension, CA199, P, tumor number, cholesterol and margin invasion." (PMID 38166611, 2024). "The correlation of T cell abnormalities with age, abnormal BMI, hypertension, and AFP levels further underscores the need for personalized approaches." (PMID 39439786, 2024). "The case presented as gradually worsening hypertension and erythrocytosis in the setting of normal surveillance scans and alpha‐fetoprotein levels." (PMID 39713744, 2024). "The expression of PAD2 was correlated with age, hepatitis B virus positivity, hypertension, and higher alpha-fetoprotein level." (PMID 36832148, 2023). "Patients with low PAD2 expression showed younger age, hepatitis B surface antigen (HBsAg) positivity, hypertension, and higher AFP level (p < 0.05)." (PMID 36832148, 2023). "Multivariate Cox regression analysis showed that metformin administration was an independent predictor for LTR (hazard ratio [HR] 0.28, 95% CI 0.14–0.58, p = 0.001), along with hypertension, pre-treatment AFP levels and tumor size." (PMID 36008432, 2022). "There were significant differences in BMI, Preoperative AFP, hypertension, and the proportion of nodal status between these two groups before PSM." (PMID 36505810, 2022). "Univariate analysis demonstrated that hypertension, larger tumor size (≥5 cm), higher AFP level (≥400 ng/mL), and high PrPC expression were potential candidates for multivariate analysis of survival (p < 0.1 on univariate analysis)." (PMID 35885540, 2022). "Further, early decrease of >20% in AFP levels following sorafenib treatment, occurrence of HFSR, hypertension, and diarrhea were associated with better overall benefits from sorafenib." (PMID 31234316, 2019). "For baseline results, nine characteristics, namely, hypertension (p < 0.001), dyslipidemia (p < 0.001), HP infection (p = 0.008), glucose (p = 0.001), pepsinogen II (p < 0.001), AFP (p < 0.001), CEA (p = 0.001), CA125 (p < 0.001), and CA199 (p = 0.003), showed significant differences." (PMID 40535142, 2025). "Total T cell abnormalities link with age, BMI, hypertension, and AFP levels in HCC patients." (PMID 39439786, 2024). "The findings of the univariate analysis indicated that hypertension (p = 0.026), a lower albumin level (p = 0.002), a higher AFP level (p = 0.035), a lower creatinine level (p = 0.018), and a higher baseline eGFR (p = 0.005) were associated with a large eGFR decline." (PMID 36766578, 2023). "Our previous retrospective analysis of PLC patients with hypertension showed that the area under the curve (AUC), sensitivity, and specificity of AFP combined with CA125 in the differential diagnosis of the OM group and non‐ocular metastasis (NOM) group were 0.875, 0.762, and 0.884, respectively." (PMID 37795569, 2023).
Hypertension (continued). "It is recommended that all patients on androgen therapy be monitored for hypertension and have a complete blood count, liver enzymes, urinalysis, serum alpha-fetoprotein, creatine phosphokinase and lipid profile performed every 6 months, and an annual liver ultrasound." (PMID 25352908, 2014). "Alpha-fetoprotein (AFP) was detected in hepatopathy (P = 1.08 × 10−28), and complex prostate-specific antigen was found in hypertension + coronary (P = 8.38 × 10−20)." (PMID 36379988, 2022). "Compared to the cohort from 2009-2013, the patients with NBNC-HCC in 2014-2018 were significantly older (p = 0.047) and had a higher BMI (p = 0.002) and higher AFP (p< 0.001), and more frequently had T2DM (p = 0.049), hypertension (p = 0.004) and MAFLD (p = 0.003)." (PMID 35186751, 2022). "Additionally, hypertension and abnormal AFP also showed significant negative correlations in the T cell abnormal group, with β values of -0.72 (95% CI = -1.79 to -0.35, P = 0.026) and -1.10 (95% CI = -2.36 to -1.03, P = 0.015), respectively." (PMID 39439786, 2024). "Seventeen relevant parameters were screened using the LASSO regression model, including hypertension, cholecystectomy, tumor number, bile duct dilatation, lymph nodes, degree of differentiation, margin invasion, CA199, boundary, gender, monocyte, P, Fe, Glu, cholesterol, GP and AFP." (PMID 38166611, 2024). "Nevertheless, males, patients with Child-Pugh score ≤7, >3 tumors, AFP level >200 mg/dL, HBV infection or vascular invasion, and patients without hypertension might benefit more than their counterparts." (PMID 35280760, 2022).
hepatitis C (56 papers, 2008 to 2025). "High LMR was associated with lower Hepatitis C prevalence, higher absolute lymphocyte count, and a trend toward lower alpha-fetoprotein." (PMID 39057108, 2024). "Univariate analysis demonstrated that age > 60 years, hepatitis C, portal vein involvement (thrombosis), tumor size > 5 cm, AFP > 400 ng/mL, serum albumin, and CRP were risk factors for poor OS." (PMID 34067711, 2021). "Regarding the screening tests that we usually use in surveillance for HCC, another aspect to discuss is that AFP measurement will probably have a better performance in patients with cured hepatitis C, particularly with an increase in its specificity." (PMID 40149352, 2025). "Similar results are expected in patients with cured hepatitis C. To improve sensitivity, a lower cut-off of AFP (around 7 ng/mL), instead of the presently proposed 20 ng/mL, should be tested in future studies." (PMID 40149352, 2025). "The best cut-off values were 5, 6, or 7 ng/mL in the different studies, which strongly point out that close attention should be paid to patients who show slightly elevated AFP levels after hepatitis C eradication." (PMID 40149352, 2025). "After adjusting for ALBI grade, AFP group, hepatitis C, insurance status, and treatment received, there was a statistical difference in hazard of death at three years (aHR: 1.9; 95% CI: 1.2, 3.1; p = 0.009), favoring the screened cohort." (PMID 39594783, 2024). "The univariate analysis revealed that an age > 60 years, hepatitis C, portal vein involvement (thrombosis), a tumor size > 5 cm, alpha-fetoprotein (AFP) > 400 ng/mL, serum albumin, and C-reactive protein (CRP) were risk factors for poor OS." (PMID 34067711, 2021). "On the other hand, log10(SCCA-IgM) and log10(AFP) were considerably higher in hepatitis C-positive patients [results reported Suppl." (PMID 31882893, 2019). "Given previous reports of improved AFP levels in patients achieving sustained virological response (SVR) to anti-Hepatitis C therapy, SVR could also be introduced to patient-specific algorithms in the future." (PMID 27308823, 2016). "It was stated that hepatic injury; such as during active hepatitis C virus infection; can increase the serum levels of AFP in patients who do not have HCC." (PMID 32986366, 2020). "The presence of type B GGT mRNA in non-cancerous liver tissue was significantly correlated with hepatitis C infection, high serum level of AFP, absence of infiltration of capsule, vascular permeation, daughter nodules, postresection recurrence, and postrecurrence survival." (PMID 22655201, 2012). "Moreover, non-Asian patients, those with hepatitis C, BCLC stage B, or AFP <400 ng/mL derived limited immunotherapy benefit across regimens." (PMID 41451207, 2025).
colorectal cancer (54 papers, 2013 to 2026). A primary or metastatic malignant neoplasm that affects the colon or rectum. "Primary AFP‐producing colorectal cancer is extremely rare and causes confusion among clinicians." (PMID 35285179, 2022). "For example, AFP-producing colorectal cancer in a 47-year-old woman metastasized to the liver and systemic lymph nodes, leading to death." (PMID 40430002, 2025). "AFP production in colorectal cancer is rare; however, AFP-producing colorectal cancer tends to be more aggressive than typical colorectal cancer and is associated with rapid progression of liver metastasis." (PMID 40430002, 2025). "In a study of colorectal cancer, it was found that a higher AFP level had higher specificity (78.60%), sensitivity (88.00%), and accuracy (83.30%) in the diagnosis of liver metastasis in patients." (PMID 40919145, 2025). "Nevertheless, since most colorectal cancer tissues are non-AFP producing, a combination of the universal colorectal cancer markers is more favorable for confirming the pathological characteristics of PDX tumors." (PMID 36742145, 2023). "Patients who have had a history of HCC with high AFP level initially diagnosed with colorectal cancer should be considered extrahepatic metastases from HCC as well." (PMID 32723336, 2020). "Here, we report a case of AFP-producing colorectal cancer which successfully responded to chemoradiotherapy." (PMID 30191347, 2018). "As for AFP-producing colorectal cancers, a similar tendency has been observed in previous reports and their reviews of up to 12 patients." (PMID 30191347, 2018). "The effectiveness of preoperative chemoradiotherapy against the AFP-producing colorectal cancer is reported here for the first time." (PMID 30191347, 2018). "Patients with AFP-producing colorectal cancer underwent several treatments, including surgery and chemotherapy according to conventional colorectal cancer treatment." (PMID 30191347, 2018). "Although the most common subtype of AFP-GC is poorly differentiated carcinoma, poorly to moderately differentiated carcinoma is commonly observed among AFP-producing colorectal cancer." (PMID 25962419, 2015). "In Japanese literature, there are only two reported cases of AFP-producing colorectal disease detected in the early stages, which were T1 N0 and T2 N0 colorectal cancer, respectively." (PMID 25962419, 2015). "This is similar to what occurs in colorectal cancer but differs from what has been reported for other cancers, such as the increased core fucosylation of alpha-fetoprotein that was observed in HCC." (PMID 24147084, 2013). "Furthermore, an analysis of 20 cases indicated that the clinicopathological features of AFP-producing colorectal cancer differ from those of typical colorectal cancer, with these patients exhibiting a higher metastasis rate and lower survival rate." (PMID 40430002, 2025). "Additionally, a case study revealed all three cases of AFP-producing colorectal cancer in which activation of the HGF/c-Met/the transcription factor c-Myc signaling pathway was observed." (PMID 38817451, 2024). "Since this primary tumor sample is AFP-positive, the unique marker AFP only found in rare cases was supposed to be more specific than other universal colorectal cancer markers in confirming the similarity of pathological characteristics between the primary tumor and tumor from the PDX model." (PMID 36742145, 2023). "A similar phenomenon also occurs in primary alpha‐fetoprotein (AFP)‐producing colorectal cancers." (PMID 35285179, 2022). "AFP-producing colorectal cancer, however, is extremely rare." (PMID 30191347, 2018). "However, it has been shown that gastric and colorectal cancers can express AFP as well, which can be used as serological biomarker." (PMID 28494767, 2017). "AFP may be a useful tumor marker in poorly differentiated colorectal cancer with neuroendocrine component patients and a prediction of early treatment response." (PMID 26976278, 2016).